RUVBL2 (RuvB like AAA ATPase 2)
Description:
Possesses single-stranded DNA-stimulated ATPase and ATP-dependent DNA helicase (5' to 3') activity; hexamerization is thought to be critical for ATP hydrolysis and adjacent subunits in the ring-like structure contribute to the ATPase activity. Component of the NuA4 histone acetyltransferase complex which is involved in transcriptional activation of select genes principally by acetylation of nucleosomal histones H4 and H2A. This modification may both alter nucleosome -DNA interactions and promote interaction of the modified histones with other proteins which positively regulate transcription. This complex may be required for the activation of transcriptional programs associated with oncogene and proto-oncogene mediated growth induction, tumor suppressor mediated growth arrest and replicative senescence, apoptosis, and DNA repair. The NuA4 complex ATPase and helicase activities seem to be, at least in part, contributed by the association of RUVBL1 and RUVBL2 with EP400. NuA4 may also play a direct role in DNA repair when recruited to sites of DNA damage. Component of a SWR1-like complex that specifically mediates the removal of histone H2A.Z/H2AZ1 from the nucleosome. Proposed core component of the chromatin remodeling INO80 complex which exhibits DNA- and nucleosome-activated ATPase activity and catalyzes ATP-dependent nucleosome sliding. Plays an essential role in oncogenic transformation by MYC and also modulates transcriptional activation by the LEF1/TCF1-CTNNB1 complex. May also inhibit the transcriptional activity of ATF2. Involved in the endoplasmic reticulum (ER)-associated degradation (ERAD) pathway where it negatively regulates expression of ER stress response genes. May play a role in regulating the composition of the U5 snRNP complex.
Synonyms: ECP-51; TAP54-beta; INO80J; TIP48; TIP49B; CGI-46; RVB2; Reptin52; ECP51; TIH2; REPTIN
Tractability: Small molecule: a structure with a bound ligand is known; it has a binding pocket of medium quality. PROTAC: UniProt records ubiquitination sites on it; ubiquitination databases record sites on it; its protein half-life has been measured.
Target class: Enzyme
Gene: Protein-coding gene on chromosome 19 (48,993,562 to 49,015,983, forward strand). Ensembl gene ENSG00000183207.
Subcellular location: Nucleus matrix; Nucleus, nucleoplasm; Cytoplasm; Membrane; Dynein axonemal particle
Subcellular location (Human Protein Atlas): Cytosol; Nucleoplasm; Basal body; Centrosome
Pathways (Reactome):
Cell Cycle: Telomere Extension By Telomerase
Chromatin organization: HATs acetylate histones
Gene Ontology:
Molecular function: ATP hydrolysis activity; beta-catenin binding; chromatin DNA binding; DNA helicase activity; identical protein binding; promoter-enhancer loop anchoring activity; protein binding; RNA polymerase II cis-regulatory region sequence-specific DNA binding; RNA polymerase II core promoter sequence-specific DNA binding; TBP-class protein binding; transcription corepressor activity; ADP binding; ATP binding; ATP-dependent activity, acting on DNA; ATPase binding; protein homodimerization activity; TFIID-class transcription factor complex binding
Biological process: cellular response to estradiol stimulus; cellular response to UV; chromatin remodeling; establishment of protein localization to chromatin; negative regulation of canonical Wnt signaling pathway; positive regulation of DNA-templated transcription; positive regulation of double-strand break repair via homologous recombination; positive regulation of transcription by RNA polymerase II; regulation of cell cycle; regulation of chromosome organization; regulation of DNA replication; regulation of DNA strand elongation; telomerase RNA localization to Cajal body; box C/D snoRNP assembly; DNA recombination; DNA repair; protein folding; protein stabilization; regulation of apoptotic process; regulation of DNA-templated transcription; regulation of double-strand break repair; regulation of transcription by RNA polymerase II; negative regulation of DNA-templated transcription; positive regulation of DNA repair; positive regulation of telomere maintenance in response to DNA damage; and 3 more
Cellular component: cytoplasm; cytosol; euchromatin; extracellular exosome; Ino80 complex; MLL1 complex; NuA4 histone acetyltransferase complex; nucleoplasm; nucleosome; nucleus; protein folding chaperone complex; R2TP complex; RPAP3/R2TP/prefoldin-like complex; Swr1 complex; dynein axonemal particle; membrane; nuclear matrix; ribonucleoprotein complex
Genetic constraint (gnomAD): Loss-of-function variants: 8 observed, 58.14 expected, observed/expected ratio (o/e) 0.14, 90% interval 0.08 to 0.25. The upper end of that interval is the gene's LOEUF score, 0.25, which puts it in group 1 of 6, group 1 being the genes least tolerant of losing a copy. Missense variants: 450 observed, 680.44 expected, observed/expected ratio (o/e) 0.66, 90% interval 0.61 to 0.71. Synonymous variants: 277 observed, 271.15 expected, observed/expected ratio (o/e) 1.02, 90% interval 0.93 to 1.13.
Homologues: Orthologues: chimpanzee RUVBL2 (100% identical), dog RUVBL2 (99% identical), mouse Ruvbl2 (99% identical), rabbit RUVBL2 (99% identical), guinea pig RUVBL2 (98% identical), macaque RUVBL2 (95% identical), rat Ruvbl2 (95% identical), tropical clawed frog ruvbl2 (94% identical), pig RUVBL2 (94% identical), zebrafish ruvbl2 (88% identical), Drosophila melanogaster rept (77% identical), Caenorhabditis elegans ruvb-2 (57% identical). Paralogues in human: RUVBL1 (42% identical).